RETN (resistin)
Diseases named in the same sentence as RETN in open-access papers (continued):
Sharing a sentence is not in itself a finding about the gene and the disease.
Obesity (continued). "Thus, we can conclude that resistin is involved in the development of obesity and its vascular complications, particularly atherosclerosis." (PMID 36499312, 2022). "Adipokines, including leptin, adiponectin, resistin and visfatin, secreted from adipose tissue and elevated in obesity, as well as cytokines and chemokines, contribute to the pathophysiology of obesity-related disorders, especially to type 2 diabetes mellitus development." (PMID 35624760, 2022). "In rodents, resistin is expressed by adipocytes and is related to obesity and ID." (PMID 35011183, 2021). "Similarly, resistin is an adipocytokine that is positively correlated with adiposity, potentially connecting obesity with insulin resistance and T2DM." (PMID 34037093, 2021). "In conditions like metabolic syndrome, overweight/obesity and Type 2 diabetes, there is increased body weight, insulin resistance, hyperglycemia, hypertension, and metabolic dysfunction including elevated levels of leptin and resistin." (PMID 33679451, 2021). "This could have important implications since plasma leptin and resistin levels correlate with adiposity, and both can be elevated in obesity and overweight conditions." (PMID 33679451, 2021). "Elevated levels of pro-inflammatory adipokines such as leptin, visfatin and resistin, as found in obese individuals, may represent another crucial pathomechanistic link for how obesity might contribute to compromised periodontal healing." (PMID 34948136, 2021). "Some reports have mentioned resistin as a factor that may represent a link between obesity and insulin dysregulation." (PMID 35011183, 2021). "Indeed, AMY1 was significantly decreased and the obesity-related salivary biomarkers resistin, MCP-1, TNF-α, IL-6 and CRP were significantly increased in overweight/obese children compared with normal weight children." (PMID 34444230, 2021). "Furthermore, the progression of obesity-related tumors is determined by the interaction of many factors, and resistin, MIF and MCP-1 play an important role in this process." (PMID 34485124, 2021). "Furthermore, serum leptin and resistin have specific roles in the regulation of adipose tissue macrophages in patients with modest obesity or early metabolic dysfunction." (PMID 34576066, 2021). "Adiponectin concentration decreases with obesity and resistin secretion increases in obesity." (PMID 34742317, 2021). "Our results show that in individuals with overweight/obesity, higher circulating levels of adiponectin, but not leptin, resistin, or visfatin, were associated with an increased RA risk." (PMID 34201946, 2021). "Adipose tissue is also an active endocrine organ that can secrete some hormones or cytokines (e.g., resistin, tumor necrosis factor-α and complement D) to participate in the immune response and treatment of obesity or cardiovascular diseases and other physiological and pathological processes." (PMID 34571718, 2021). "Thus, the role of resistin in the pathology of obesity and the development of Type 2 diabetes still requires clarification." (PMID 33679451, 2021). "Growing evidence has indicated that resistin is upregulated in BC patients, yet the mechanisms of resistin on adjusting BC behavior during obesity are still largely unknown." (PMID 34350120, 2021). "A recent systematic literature review and meta-analysis, including fifteen studies found that resistin levels were weakly correlated with insulin resistance in T2DM and obesity, but this association was stronger in subjects with hyperresistinemia (≥ 14.8 ng/ml)." (PMID 34496965, 2021). "Levels of serum resistin, an adipocytokine secreted by fat tissues, increase with obesity." (PMID 34349610, 2021). "Adipocytes are important endocrine cells in the tumor microenvironment of obesity-related tumors, which can secrete a variety of adipokines (such as leptin, adiponectin, estrogen, resistin, MIF and MCP-1, etc.), among which leptin, adiponectin and estrogen are the most in-depth and valuable ones." (PMID 34485124, 2021).
Obesity (continued). "A recent meta-analysis suggests that type 2 diabetes and obesity do not necessarily need to be associated with resistin, but when resistin displays high circulating levels insulin resistance occurs." (PMID 34680059, 2021). "Melatonin supplementation was reported to improve obesity‐induced resistin elevation." (PMID 33532613, 2021). "Obesity causes changes in the circulating levels of adiponectin, leptin, and resistin by adipocytes, which can act as a regulatory link between the endocrine system and the immune system, playing a role in the relationship between obesity, asthma, and diabetes." (PMID 33520042, 2021). "PPARγ is involved in resistin expression, which is strictly related to obesity and type 2 diabetes." (PMID 32463311, 2020). "In the obesity-induced model of osteoarthritis in mice the pro-inflammatory cytokines adiponectin, resistin and IL-649-52 contribute to the chondrocyte and cartilage defects observed and these and other adipokines have been proposed as biomarkers of osteoarthritis." (PMID 32778777, 2020). "We believe that obesity-induced inflammation (increased resistin levels) may lead to lipolysis inhibition (decreased HSL in Dox-H vs. Dox-L mice) in mammary adipose tissue." (PMID 32257945, 2020). "For example, the adipokine resistin is elevated in obesity and type 2 diabetes." (PMID 33097799, 2020). "The last studied protein resistin promotes 3T3-L1 preadipocyte differentiation and is an important mediator of obesity-induced insulin resistance; moreover, this protein could be secreted by adipocytes and is involved in insulin regulation." (PMID 32463311, 2020). "The development of IR in T2DM and obesity is influenced by both resistin and TNF-α." (PMID 33456608, 2020). "Adiponectin serves as a protective factor to prevent obesity occurrence and/or progression by suppressing inflammation, promoting fatty acid oxidation, and improving insulin sensitivity, while resistin is important in maintaining homeostasis of insulin action, energy, glucose, and lipids." (PMID 32586265, 2020). "Moreover, pro-inflammatory adipokines (resistin, fetuin-A, chemerin, leptin) are over-expressed in the adipocytes in obesity and adipokines with mainly anti-inflammatory effects (adiponektin, omentin) are supressed." (PMID 33092646, 2020). "Thus, IL-33 had a protective effect against obesity, insulin resistance and diabetes in animal models due to the reduction of resistin expression, accumulation of Th2 cells and IL-5, IL-13 and the suppression of T effectors cells by IL-10 releasing." (PMID 32824505, 2020). "Cytokines are closely related to obesity, such as resistin, leptin, adiponectin, and TNF-α." (PMID 32439940, 2020). "The knowledge about resistin and its relationship with obesity and cancer is still scarce." (PMID 32903534, 2020). "Also, high levels of resistin have been detected in the gingival crevicular fluid (GCF) of patients with obesity." (PMID 32410876, 2020). "The majority of the published data deal with the potential correlations between circulating leptin, adiponectin, and resistin levels with systemic inflammation and cachexia in obesity-related cancers, while data regarding resistin, visfatin, apelin are more limited." (PMID 32660156, 2020). "Therefore, this study was aimed to evaluate the impact of NSPT on clinical parameters, serum resistin level and periodontal pathogen count in periodontitis patients with obesity and with normal weight." (PMID 32059714, 2020). "Resistin is an adipokines closely related to obesity, local low-level inflammation and MS." (PMID 33409277, 2020). "In fact, resistin could be considered a linking hormone between obesity and diabetes (“resistin” indicates resistance to insulin)." (PMID 32660156, 2020). "Furthermore, in a screen of adipokine abundance in androgen treated IMBATS, we observed a significant reduction in adiponectin (an “anti-obesity” adipokine) and resistin expression while PAI-1 was significantly increased." (PMID 33383677, 2020).
Obesity (continued). "Its circulating levels in animal models of obesity and diabetes are increased, suggesting a deregulation of resistin production in these conditions, and both in vivo and in vitro studies have shown that resistin exerts an inhibitory effect on glucose uptake in murine adipocytes and muscle cells." (PMID 33081064, 2020). "The relationships between circulating resistin concentrations and LVM beyond indices of obesity (BMI or waist circumference) despite the high proportion of participants with obesity in the current study, suggest that the adverse effects of resistin on LVM are through effects beyond adipose tissue." (PMID 32000666, 2020). "However, the link between resistin, obesity and insulin resistance is inconsistent in humans, with some studies showing a positive association between serum resistin and insulin resistance, while others report no such relationship." (PMID 30778042, 2019). "Also consistent with previous reports, we found that, with the exception of resistin, all other adipokines including their ratios were strongly and more correlated with various obesity indices among women with aPCOS compared to the controls." (PMID 31416473, 2019). "Among these adipokines, resistin is described as a hormone linking obesity to type 2 diabetes." (PMID 30906281, 2019). "The role of resistin in obesity and adipogenesis is controversial." (PMID 31873127, 2019). "The adipokines leptin, resistin, and TNF-α are also involved in glucose metabolism, but unlike adiponectin, their elevated levels are associated with the development of diabetes and obesity." (PMID 31514360, 2019). "However, resistin levels can be influenced by a variety of factors, such as the presence of atherosclerosis, obesity or sepsis." (PMID 31881807, 2019). "Moreover, melatonin was effective in decreasing the levels of leptin and resistin in plasma of animals induced to obesity by an HFD." (PMID 31489938, 2019). "The adipokine resistin exhibits proinflammatory, proangiogenic and metastatic properties, and evidence suggests that resistin may serve as a prognostic biomarker linking obesity and inflammation to cancer." (PMID 31719210, 2019). "The adipokines leptin, adiponectin, resistin and omentin are thought to have important roles in human obesity and glucose homeostasis; however, their functions in the pathophysiology of feline diabetes mellitus and obesity are poorly understood." (PMID 31533709, 2019). "It is suggested that resistin links obesity to type 2 diabetes." (PMID 31195622, 2019). "The expression and secretion of MCP-1, IL-6, and resistin are increased in obesity, playing an important role in the appearance of the inflammatory M1 type macrophages, and decreasing the expression and production of the protective adiponectin and IL-10 in the adipose tissue." (PMID 31438590, 2019). "Loss of TG2 did not affect the obesity-related alterations in the expression levels of the adiponectin and resistin, but obesity-induced expressions of TNF-α, MCP-1, and leptin were significantly enhanced in the gWAT adipocytes of TG2 null animals as compared to wild type mice." (PMID 31165747, 2019). "Numerous studies have found a significant correlation between obesity and many autoimmune diseases, adipokines such as leptin, adiponectin and resistin may be key players in interactions among them." (PMID 31118946, 2019). "Therefore, it is postulated that resistin represents a molecular link between obesity and type 2 diabetes." (PMID 31772701, 2019). "Like leptin, resistin is positively correlated with obesity." (PMID 31316526, 2019). "Under fasting conditions, decreased resistin partly reduced hepatic glucose production by activating AMPK and inhibiting hepatic gluconeogenic enzymes, and regulating hyperglycemia associated with obesity." (PMID 31208019, 2019).
Obesity (continued). "A smaller share is attributed to genetic factors, which include the polymorphism of following genes: fat mass and obesity-associated gene (FTO), commonly referred to as the “obesity gene”, and gene coding for peroxisome proliferator-activated receptor gamma (PPARγ), resistin, and adiponectin." (PMID 31737129, 2019). "Additionally, LPS has been repeatedly shown to positively related to obesity and especially adipocytokines, such as SC-LCBs-increased adiponectin, and decreased leptin, resistin, and TNF-α." (PMID 31374958, 2019). "In obesity, when type 2 diabetes occurs, resistin levels increase and adiptonectin decreases." (PMID 31195622, 2019). "One study on postmenopausal women found an association between increased resistin levels and the risk of stroke, regardless of the presence of obesity and other risk factors for cardiovascular disease, a conclusion not confirmed by another large study." (PMID 30405857, 2018). "Although all mechanisms underlying the link between obesity and IR are not entirely clear, it is known that hormones and cytokines such as resistin, tumor necrosis factor (TNF-α), and interleukin-6 (IL-6) secreted by adipocytes unbalance the action of insulin." (PMID 30513771, 2018). "Among the top modulated adipokines were inflammatory mediators (C-reactive protein, endocan, EN-RAGE), extracellular matrix regulating factors (Serpin A8, TIMP-1, TIMP-3), and resistin, an adipokine proposed to be an important link between obesity and diabetes." (PMID 30524378, 2018). "Recent evidence suggests that in addition to storing energy, adipose tissue may secrete several inflammatory factors, such as resistin, vaspin and visfatin, which may be important mediators of obesity, atherosclerosis, and DM." (PMID 29848323, 2018). "Both leptin and resistin are two of the important adipokines, which are elevated in obesity." (PMID 29568521, 2018). "Therefore, resistin has pro-inflammatory properties and its increased levels indicate the development of insulin resistance, diabetes, obesity, and cardiovascular disease." (PMID 30200554, 2018). "The adipokine resistin has been proposed to link obesity, insulin resistance and diabetes." (PMID 30353146, 2018). "In the setting of obesity, resistin acted as adipocytokine and possessed proinflammatory property." (PMID 30398974, 2018). "The impairment of insulin-evoked vasorelaxation by resistin may represent an important link between changes in adipokines and CVDs in obesity." (PMID 30416448, 2018). "Obesity-related low-grade inflammation originates from the adipose tissue, which enables the secretion of a variety of interleukins and adipokines such as leptin, adiponectin, and resistin." (PMID 30050954, 2018). "Thus, the targeting effect of coconut water vinegar on RBP4 and resistin clearly indicated its effectiveness in ameliorating obesity and in assisting in the reduction of serum LDL levels." (PMID 29056887, 2017). "Current evidence suggests that resistin represents a link between obesity and type 2 diabetes." (PMID 28421123, 2017). "Resistin is a novel adipocytokine that may play a role in the pathophysiology of insulin resistance and obesity." (PMID 28747175, 2017). "On the other hand, resistin has been linked to obesity and IR since its discovery, but our results are not consistent with these findings because we found a weak negative correlation between resistin levels and HOMA-IR (R = −0.274 and p = 0.045)." (PMID 28587203, 2017). "Adiponectin, leptin, and resistin are adipocytokines that are related to obesity." (PMID 28246535, 2017). "Resistin, while classified as an adipokine, is a protein produced primarily by macrophages in humans and, when first discovered, was thought to provide a link between obesity and insulin resistance." (PMID 28611687, 2017).
Obesity (continued). "Notably, the mean resistin protein level was higher in obese individuals who suffered from obesity-related complications than in “healthy” obese subjects both in VAT (P = 0.005) and SAT (P = 0.017)." (PMID 29213336, 2017). "Examining the role of resistin in obesity-related colorectal carcinogenesis remains difficult." (PMID 28422056, 2017). "The interplay between adiponectin and resistin, the two adipokines of opposite effects, may determine the metabolic profile of obese individuals and development of obesity-related complications." (PMID 29213336, 2017). "Secreted by adipocytes, the protein coding by RETN may link obesity to type II diabetes considering its functional biological functions on regulating insulin activity and biological source." (PMID 29258237, 2017). "The links between resistin and obesity need further investigations." (PMID 29142618, 2017). "We also showed that obesity affects synthesis of adiponectin and resistin mainly in SAT." (PMID 29213336, 2017). "Data suggests that resistin could be one of the molecular links connecting obesity, diabetes, and periodontitis and may serve as a link between periodontal diseases and other systemic diseases." (PMID 29138754, 2017). "Obesity affects synthesis of adiponectin and resistin mainly in subcutaneous adipose tissue." (PMID 29213336, 2017). "Adipokines such as leptin, adiponectin, resistin and PAI-1 are physiologically active cytokines secreted from adipocytes that play an important role in the pathogenesis of MS through inflammation associated with obesity, atherosclerosis and diabetes." (PMID 29258500, 2017). "High leptin levels are associated with obesity, insulin resistance, and metabolic syndrome, and conversely elevated plasma adiponectin levels are associated with decreased risk of T2DM, while associations for resistin are contradictory." (PMID 28413567, 2017). "Obesity in humans was found to be associated with high resistin serum levels, this view however is not unanimous." (PMID 29213336, 2017). "Adipokine resistin is an important factor linking obesity with diabetes." (PMID 28097156, 2016). "Due to resistin’s inflammatory properties and role in adipose tissue, it may be a link between inflammation, obesity, and cancer." (PMID 27314854, 2016). "Thus, wedesigned this study to investigate the relationship between changes in resistin andleptin levels with obesity and CAD." (PMID 27627223, 2016). "More convincing evidence is needed to reveal the role of resistin in obesity-related cancers." (PMID 27509174, 2016). "We hypothesized that treatment with tomato and broccoli extracts regulates glucose homeostasis via modulation of resistin levels in high fat diet-induced obesity rats (HFD)." (PMID 27430475, 2016). "Besides resistin, leptin is another increased physiological factor in obesity which also comes from adipose tissue." (PMID 27663646, 2016). "Interestingly, miR-96 was upregulated in the liver of insulin resistant mice injected with resistin, which is considered a potential adipokine responsible for obesity-mediated insulin resistance, T2DM, and inflammation." (PMID 28036389, 2016). "The direct correlation between these cytokines and the Arg64/X variant is not known, but low visfatin and high resistin concentrations are characteristic for obesity state and correlate with the risk of diabetes mellitus." (PMID 27246401, 2016). "Furthermore, serum resistin and leptin have specific roles in the regulation of adipose tissue macrophages in patients with modest obesity or early metabolic dysfunction." (PMID 27101398, 2016). "Currently, increased attention has been paid to the role of resistin in obesity-related cancers." (PMID 27509174, 2016).